BAG1 (BAG cochaperone 1)
Diseases named in the same sentence as BAG1 in open-access papers (continued):
Sharing a sentence is not in itself a finding about the gene and the disease.
cancer (continued). "Low expression of BAG1 in KIRC was significantly associated with Sex, clinical pathological stage, tumor-node-metastasis (TNM) stage, hemoglobin levels, cancer status and history of neoadjuvant treatment." (PMID 33581726, 2021). "Bag-1 is overexpressed in many types of cancer, including breast, prostate, and non-small cell lung cancers." (PMID 34428256, 2021). "Given the well-established role of Bag-1 in cancer cell survival, it is a promising molecular target for the treatment of cancer." (PMID 34428256, 2021). "We previously identified a transcriptional target of MYC, termed BAG1, which is frequently overexpressed in human cancer and predictive of poor prognosis." (PMID 30902071, 2019). "Bag-1 interacts with C-Raf, B-Raf and Akt kinases, which are key mediators of cell survival and growth, and are frequently activated in cancer." (PMID 31883527, 2019). "Another gene with a potential role in cancer, which was also under positive selection, and remained significant after FDR correction, was Bag1 (Bcl2 associated athanogene)." (PMID 28132643, 2017). "At a cellular level BAG-1 can promote cancer progression which is characterized by evasion of apoptosis, through the emergence of chemo-resistance and self-sufficiency in growth signals, as shown by growth-factor independent survival." (PMID 26958811, 2016). "Elevated expression of Bag1 and Bag3 in each case signals a poor prognosis for cancer bearing patients." (PMID 24278769, 2013). "Hsp70 cochaperones Bag1, Bag3, and Hop play significant roles in the etiology of some cancers as do Hsp90 cochaperones Aha1, p23, Cdc37, and FKBP1." (PMID 24278769, 2013). "TGFB3, GINS3 and BAG1 have also been reported to be involved in cancer cell proliferation and invasion." (PMID 23977152, 2013). "Different BAG-1 isoforms have different biological functions in different cancer cell lines and tissues." (PMID 22567091, 2012). "Current studies are investigating the role of FLJ20420 in the production and function of different BAG-1 isoforms in various normal and cancer tissues." (PMID 22567091, 2012). "In HeLa cells, down-regulation of BAG-1 conferred resistance to anti-cancer drugs, including actinomycin D, camptothecin, paclitaxel, staurosporine, thapsigargin and etoposide." (PMID 22179630, 2012). "In summary, our study showed that knockdown of Bag-1 in the SCC-13 carcinoma cell line enhanced spontaneous apoptosis and sensitised the cells to apoptosis induced by 5-FU." (PMID 21522149, 2011). "The predictive value of high BAG-1 expression was greatest in ER+ cancer in which a high nuclear expression was an independent predictor of prognosis for local recurrence, distant metastases and death." (PMID 19066611, 2009). "Functional studies show that BAG-1 isoforms promote the survival, proliferation and metastasis of cancer cells." (PMID 19293798, 2009). "More recently, BAG-1 featured as one of the 16 cancer-specific genes included in the Oncotype Dx assay, which predicts distant failure in ER+, lymph node-negative patients treated with tamoxifen using PCR of formalin-fixed paraffin-embedded (FFPE) material." (PMID 19066611, 2009). "Our data implicate BAG-1 as a key player in oncogenic transformation by Raf and identify it as a potential molecular target for cancer treatment." (PMID 15560850, 2004). "Consistent with its effects on a diverse range of important cell growth control pathways, there is increasing evidence that BAG-1 expression is frequently altered in human cancer." (PMID 12373595, 2002). "Given the impact of BAG-1 overexpression on multiple growth control pathways, there has been considerable interest in studying the significance of BAG-1 in human cancer." (PMID 12373595, 2002).
cancer (continued). "The pathways regulated by BAG-1 play key roles in the development and progression of cancer and determining response to therapy, and there has been considerable interest in determining the clinical significance of BAG-1 expression in malignant cells." (PMID 12373595, 2002). "This review summarises recent progress in understanding the clinical significance of BAG-1 expression in cancer in light of our understanding of BAG-1 function." (PMID 12373595, 2002). "There are several reports to indicate that the expression of BAG-1 correlates with the malignant potential of other carcinomas." (PMID 12402153, 2002). "BAG-1 interacts with a wide range of molecular targets to regulate multiple cellular pathways (including apoptosis, proliferation, metastasis, and nuclear hormone receptor transactivation) important for the development and progression of cancer." (PMID 38412481, 2024). "Finally, our observations are consistent with the development of BAG-1 KO embryonic stem cells that maintained pluripotency and the ability to differentiate, and studies of cancer cell lines where BAG-1 is rarely essential for cell survival." (PMID 38412481, 2024). "As to whether an enhanced Rb/GR/BAG-1 nuclear translocation is relevant to the pathogenesis of cancers, e.g., via enhanced TDO upregulation, will be interesting to determine, including how circadian melatonin interacts with Rb." (PMID 37970210, 2023). "Bag-1 protein is a crucial target in cancer to increase the survival and proliferation of cells." (PMID 34995286, 2022). "For the interactome analysis we used MCF-7 cells, reasoning that interactions identified in these cells might give insights into the role of Bag-1 isoforms in cancer." (PMID 34428256, 2021). "Targeting the interactions between Bag-1 and its binding partners with small molecules might be an effective therapeutic strategy to release inhibition of apoptosis in Bag-1 overexpressing cancer cells." (PMID 31883527, 2019). "The concept that BAG-1, a protein that supports cancer cell survival, is related to improved patient survival may seem paradoxical." (PMID 28510570, 2017). "Since BAG-1 protein is frequently expressed in various of cancers, including HNSCC, it is intriguing to see whether a longer duration of high BAG-1 expression is associated with cisplatin resistance of UMSCC cells." (PMID 28877725, 2017). "The concept of targeting BAG-1, a protein that supports cancer cell survival but is also related to improved patient survival, may on the surface seem paradoxical." (PMID 26958811, 2016). "It stimulates the translation of c-myc and Bag-1, having an anti-apoptotic effect on cancer cells." (PMID 25136288, 2014). "The two family members with most significance in cancer appear to be Bag1 and Bag3." (PMID 24278769, 2013). "The BAG-1, as an anti-apoptotic function, exhibits positive expression in many malignant tumors." (PMID 22439756, 2012). "Moreover, overexpression of BAG-1 has been found in many forms of cancers, including breast, lung, squamous cell carcinomas and glioblastoma." (PMID 22179630, 2012). "Moreover, expression of another anti-apoptotic Bcl-2 family gene, Bag-1, was unchanged in the three non-cancer cells." (PMID 20969773, 2010). "The ability of high nuclear BAG-1 expression to predict improved outcome in ER+ cancer and also in those treated with tamoxifen is of potential mechanistic importance as it suggests that it may have a role in responsiveness to adjuvant endocrine therapy." (PMID 19066611, 2009). "Functional and expression studies suggest that overexpression of BAG-1 may play an important role in diverse cancer types." (PMID 19293798, 2009). "This study demonstrates that a high BAG-1 expression identifies a good prognosis group of cancers with a luminal A phenotype, which may have enhanced therapeutic sensitivity to tamoxifen." (PMID 19066611, 2009).
cancer (continued). "It is becoming increasingly clear that expression of BAG-1 is frequently altered in human cancer and it is possible that expression analysis might be of clinical utility." (PMID 12373595, 2002). "A second key function of BAG-1 of likely importance for cancer is regulation of NHR." (PMID 12373595, 2002). "We believe that it is not clear whether the discrepant results are in conflict, since the differences of BAG-1 localisation in cancer cells indicate different expression of BAG-1 isoforms, which may well have different biological functions." (PMID 12402153, 2002). "The aging-linked decrease in melatonin and BAG-1 enhances GR nuclear translocation, with consequences not only for cancer pathogenesis but also for the nature of patterned immune responses, and intercellular interactions within a given microenvironment, including the tumor microenvironment." (PMID 37970210, 2023). "In addition to the anti-apoptotic effect of BAG-1 during cancer development, BAG-1 may also contribute to drug resistance of chemotherapy." (PMID 22179630, 2012). "However, it is currently unknown how BAG-1 expression is regulated at the molecular level, especially in cancer cells." (PMID 22567091, 2012). "Therefore, the therapeutic efficacy of a standard chemotherapeutic agent should be increased dramatically by co-application with a BAG-1 inhibitor, since it would target the adaptability of cancer cells to environmental stress and overcome their genetic plasticity." (PMID 15560850, 2004). "Therefore, in addition to contributing to reduced cell death in cancer development, BAG-1 may also contribute to resistance to important therapeutic modalities." (PMID 12373595, 2002). "Thus, we infer that BAG1 may inhibit cancer progression in KIRC vial localizing in the cytoplasm." (PMID 33581726, 2021). "The subgroups include proliferation genes (Ki67, STK15; Survivin, CCNB1, MYBL2), invasion genes (MMPP11, CTSL2), HER2 genes (GRB2, HER2), estrogen genes (ER, PGR, BCL2, SCUBE2), and other cancer related genes (GSTM1, CD68, BAG1)." (PMID 33665165, 2020). "BAG-1, BCL-2 and ER feature among the 16 cancer-related genes of the Oncotype Dx assay, which predicts distant failure in ER+ lymph node-negative patients treated with tamoxifen." (PMID 19066611, 2009). "Even though the vast majority of our hits are known essential genes in human cancer cell lines or human iPSC-derived neurons, this method reveals some unique hits that have not been previously reported, including Jtb, Snx17, Psph, Bag1, and Becn1." (PMID 37398301, 2024). "The cancer genes are composed of genes that code for HER2 (HER2 and GRB7), oestrogen genes (ER, PGR, BCL2, and SCUBE2), proliferation genes (MKI67, STK15, BIRC5, CCNB1, and MYBL2), and invasion genes (MMP11 and CTSL2) as well as GSTM1, CD68, and BAG1." (PMID 36042999, 2022). "In contrast, ANGPTL2, BAG1, and CDH2 were mainly expressed in cancer cells and oligodendrocytes." (PMID 36291283, 2022). "Thus, BAG-1 is considered as being a possible therapeutic target in CRC, as well as in other cancer types." (PMID 31504805, 2019). "In the epidermal dysplasia and carcinoma cell lines, Bag-1 protein was overexpressed relative to normal keratinocytes." (PMID 21522149, 2011). "Importantly, the BAG-1:HSC70/HSP70 interaction is reported to be critical for BAG-1 function and therefore therapies targeting this interaction are an attractive strategy to overcome BAG-1 function in cancer." (PMID 38412481, 2024). "In addition, based on the evidence that cancer cells develop drug resistance by inducing the UPR, the Bag-1 peptide could be used to overcome this problem and to potentiate the anti-tumorigenic effect of already existing drugs." (PMID 23049684, 2012).
cancer (continued). "Moreover, BAG1 and BAG3 have been involved within the Mitogen-Activated Protein Kinase (MAPK) pathway, principally through c-RAF activation, and separate studies confirmed either BAG1 or BAG3 deregulation in diverse cancer types." (PMID 22016818, 2011). "Thus, we should not expect a simple pattern of changes in BAG-1 expression in all cancer types due to differences in ‘key’ BAG-1 targets in different cell types." (PMID 12373595, 2002). "Their study revealed that anti-cancer drugs such as dexamethasone, daunorubicin, and the BCL2 inhibitor ABT-737 exhibited greater sensitivity in BAG1-depleted cells without any toxicity, whereas pan-BCL inhibitors caused cytotoxic effects in zebrafish." (PMID 38611039, 2024). "The nuclear/cytoplasmic distribution of BAG-1 isoforms is regulated under some conditions and it is important to recognise that nuclear BAG-1 immunostaining in cancer cells may not be a reliable measure of BAG-1L expression." (PMID 12373595, 2002).
tumor (44 papers, 1999 to 2025). "In HER2-positive disease, our findings associate genes such as ARG2, S100A1, MT2A, EIF4EBP1, KLF4, BTG3, and BAG1 to be associated with favourable prognosis through their roles in metabolic regulation, oxidative stress mitigation, and tumour suppression." (PMID 41007296, 2025). "At multivariate analysis, BAG1 remained independently associated with overall survival, with a HR of 1.75(CI:1.05–2.90, p = 0.029), along with tumor size, stage, lymph nodes and distant metastasis." (PMID 33581726, 2021). "To search the biological mechanism of BAG1 in KIRC, we performed the GSEA to identify the tumor-associated pathways or gene sets that altered between the patients with low BAG1 expression and those with high BAG1 expression." (PMID 33581726, 2021). "Nuclear and cytoplasmic BAG-1 expression was associated with low-grade tumours, ER and PgR positivity, and improved overall survival but was negatively correlated with HER2 and the triple-negative phenotype." (PMID 28510570, 2017). "Increased expression of BAG-1 was associated with cisplatin resistance and tumor progression in HNSCC patients and warrants further validation in larger independent studies." (PMID 28877725, 2017). "The percentage of Bag-1 positive cells in the tumour also showed an association with differentiation (P=0.007), indicating a link between Bag-1 protein and reduced differentiation status." (PMID 21522149, 2011). "This also provides a distinct perspective as to how variations in melatonin/BAG-1/GR can modulate the homeostatic interactions of the tumor microenvironment over the circadian rhythm." (PMID 37970210, 2023). "In an ILT-Mat tumor cell line and hepatoma cells, butyrate suppresses BAG-1 levels, thereby decreasing tumor survival." (PMID 37970210, 2023). "The current study found that the KIRC tumor samples have a low level of BAG1 mRNA expression compared to the matched normal tissues based on TCGA data and GEO databases." (PMID 33581726, 2021). "In recent years, increasing evidence has indicated that the pivotal role of BAG1 involved in the pathogenesis or progression of tumor." (PMID 33581726, 2021). "We also collected gene expression data from renal tumors and normal kidneys in GEO data (series GSE105288) to detect the difference in BAG1 expression levels between normal and tumor group." (PMID 33581726, 2021). "To further strengthen the evidence differences in BAG1 expression level between tumor and normal tissues, we retrieved another gene expression data from GEO (series number: GSE105288)." (PMID 33581726, 2021). "The formula of the F2P Score was developed and presented herein: F2P Score = 0.888 × (1.424 × tumor size-0.667 × age)+0.314 × (−0.259 × ESR1−0.191 × PGR−0.292 × BCL2−0.226 × GSTM1 −0.457 × CD68–0.320 × BAG1)." (PMID 33042787, 2020). "We found that Bag-1 expression was significantly higher in tumor cells than in normal cells in all subtypes." (PMID 31883527, 2019). "BAG1 expression is a biomarker of poor prognosis, presumably because it activates a pro-survival pathway that tumor cells need in order to proliferate." (PMID 30902071, 2019). "We investigated the interactions between Bag-1, Akt and Raf kinases in cell lines and tumor tissues by co-immunoprecipitation, and their subcellular localization by immunocytochemistry and immunohistochemistry." (PMID 31883527, 2019). "We demonstrate here that it is specifically the S isoform of BAG1 that provides the survival function in MYC overexpressing tumor cells." (PMID 30902071, 2019).